KCNJ11 (potassium inwardly rectifying channel subfamily J member 11)
Diseases named in the same sentence as KCNJ11 in open-access papers (continued):
Sharing a sentence is not in itself a finding about the gene and the disease.
Hyperglycemia (25 papers, 2010 to 2025). An increased concentration of glucose in the blood. "NGS helped switch the management of hyperglycemia from unnecessary insulin injections to glibenclamide in 8 of our patients with KCNJ11 mutations." (PMID 39504571, 2025). "ADRB3-rs4994 and ABCC8-rs1799854 genes showed a significant association with BMI and waist circumference, and the KCNJ11-rs5219 gene with hyperglycemia." (PMID 35560161, 2022). "The low p-values (<0.05) from association of KCNJ11 (rs5219) with hyperglycemia, on the other hand, is in line with that observed in other populations." (PMID 35560161, 2022). "The ABCC8 (rs1799854) gene and the KCNJ11 gene (rs5219) showed lower p-values (<0.05) in association analysis with BMI and hyperglycemia, respectively, under dominant and co-dominant models, although not statistically significant when Bonferroni correction is considered." (PMID 35560161, 2022). "In this article, a premature neonate presented to our facility for persistent hyperglycemia and was ultimately discovered to have NDM and be positive for a heterozygous pathogenic variant, c.679G>A (p.Glu227Lys), in KCNJ11." (PMID 40309172, 2025). "Activating KCNJ11 and ABCC8 mutations cause the KATP channels to remain inappropriately open even in the presence of hyperglycemia." (PMID 34566892, 2021). "Mild hyperglycemia and the history of the previous HY point toward ABCC8/KCNJ11 or HNF1α/4α mutations, especially in late onset cases." (PMID 32928245, 2020). "Despite the low prevalence of nutritional and metabolic alterations in most of the analyzed indigenous groups, a significant association was found between the ADRB3 gene and abdominal obesity and excess weight, and the KCNJ11 gene with hyperglycemia for indigenous people in general." (PMID 35560161, 2022). "Activating mutations in either the KCNJ11 or ABCC8 genes encoding the two subunits (Kir6.2 and SUR1, respectively) of the ATP-sensitive potassium (KATP) channel of the β-cell membrane, prevent insulin secretion in response to hyperglycaemia and can cause both PNDM and TNDM." (PMID 24051999, 2013).
Obesity (22 papers, 2009 to 2025). Accumulation of substantial excess body fat. "A study of carbohydrate metabolism in patients with T2D and obesity with variants of the KCNJ11 gene revealed a significant difference in HbA1c and glycemia between the groups studied." (PMID 34289004, 2021). "In addition, the m6A methylation levels of genes related to these diseases also changed after DBS; such changes occurred with Slc1a6 (an OCD-associated gene: hypermethylation), Kcnj11 (an obesity-associated gene: hypermethylation), and Dusp1 (an addiction-associated gene: hypermethylation)." (PMID 33343932, 2020). "As the higher level of glycated hemoglobin, pre- and postprandial glycemia are indicators of T2D and obesity, the C/C genotype of the KCNJ11 gene seems to have the best prognosis." (PMID 34289004, 2021). "Proportion of persons with obesity ranged from 0% (KCNJ11‐MODY) to 66.7% (KLF11‐MODY)." (PMID 39511990, 2024). "The risk of obesity (BMI) is related to the NRBP1, KIF11, and KCNJ11 genes." (PMID 38915894, 2024). "Besides FTO polymorphisms, KCNJ11 rs5219, KCNQ1 rs2237892, and TCF7L2 rs7901695 variations have previously been linked to obesity in patients with T2DM." (PMID 34442333, 2021). "Furthermore, calorie restriction and obesity have drastic opposing effects on pro- and anti-inflammatory genes as well as genes involved in adipose tissue energy metabolism such as Lpin2, Kcnj11 and Rbp4." (PMID 20307313, 2010). "It was previously demonstrated that the genetic effects of variants associated with either insulin secretion (like for GCK, KCNJ11 or TCF7L2) or insulin action (for ENPP1, ADIPOQ or PPARG) may be modulated by the obesity status or adiposity." (PMID 19368707, 2009). "We genotyped nine SNPs reported in GWAS of obesity and/or T2D, including SNPs in HHEX, KCNJ11, SLC30A8, FTO, CDKN2, CDKAL1, TCF2, and the rs9300039 SNP in an intergenic region, in 561 colon cancer cases and 721 population controls." (PMID 27990199, 2009). "We show that the CR increased the expression levels of anti-inflammatory genes Il-10 and Adrbk1 and energy homeostasis-related genes such as Ptgds, Lpin2, Angptl6, Kcnj11, and Dusp9 but were not affected by obesity in HF mice." (PMID 20307313, 2010).
epilepsy (21 papers, 2013 to 2026). A brain disorder characterized by episodes of abnormally increased neuronal discharge resulting in transient episodes of sensory or motor neurological dysfunction, or psychic dysfunction. "Our data are consistent with recent studies exploring the physiological consequences of human mutations in the KCNJ11 gene that result in clinical developmental delay, epilepsy, and neonatal diabetes or DEND syndrome." (PMID 39964713, 2025). "More than 130 mutations have been reported in KCNJ11, which cause psychomotor developmental delay and epilepsy during the infantile period with the most severe form." (PMID 37483435, 2023). "A previously reported heterozygous KCNJ11 missense mutation, p.C166Y, was identified in the third patient who had developmental delay, epilepsy, and neonatal diabetes syndrome." (PMID 28943513, 2018). "Approximately 25% of patients with a mutation of the ABCC8 or KCNJ11 genes have neurological disorders ranging from psychomotor disorders to delayed cognitive development associated with severe epilepsy (DEND syndrome: Developmental delay, Epilepsy, and Neonatal Diabetes)." (PMID 33102403, 2020). "Mutations in KCNJ11 are frequently associated with PNDM and, in severe cases, the DEND syndrome (Developmental delay, Epilepsy, and Neonatal Diabetes)." (PMID 41614934, 2026). "Neurological: KCNJ11 mutations can cause DEND syndrome (developmental delay, epilepsy) due to channel expression in the brain." (PMID 41614934, 2026). "We identified four key potassium channel genes, KCNA1, KCNA2, KCNJ11, and KCNS1, that are associated with the pathogenesis of epilepsy." (PMID 37483435, 2023). "Since Kir6.2 is expressed in skeletal muscle, peripheral nerves, and the brain, specific KCNJ11 variants are associated with developmental delay and epilepsy, collectively known as developmental delay, epilepsy, and NDM (DEND) syndrome." (PMID 41498801, 2026). "Similar cases of PNDM with neurological sequelae have been reported, particularly in KCNJ11 or ABCC8 mutations, where epilepsy may arise from direct channelopathy effects." (PMID 41393705, 2025). "Another syndromic form of NDM is DEND syndrome (developmental delay, epilepsy, and neonatal diabetes) (OMIM#618856) caused by severe mutations in the KCNJ11 gene, leading to NDM together with epilepsy, severe developmental delay, muscle weakness, and dysmorphic features." (PMID 39408828, 2024). "Here we report three patients with neonatal diabetes; two with isolated pancreas agenesis due to mutations in the pancreas-specific transcription factor 1A (PTF1A) enhancer and one with developmental delay, epilepsy, and neonatal diabetes (DEND) syndrome, due to a KCNJ11 mutation." (PMID 28943513, 2018). "Gain of channel function (GOF) mutations in the genes encoding Kir6.2 (KCNJ11) or the associated regulatory ssulfonylurea receptor 1 subunit (ABCC8), cause developmental delay, epilepsy and neonatal diabetes (DEND) due to suppressed cell excitability in pancreatic β-cells and neurons." (PMID 23667671, 2013). "Previous research has shown that three of the four key potassium channel genes (KCNA1, KCNA2, KCNJ11, and KCNS1) play vital roles in seizures and epilepsy." (PMID 37483435, 2023). "We sequenced KCNJ11 and BAD in individuals without previously-known glucose transporter type 1 deficiency syndrome or other metabolic disorders, who received KDT for epilepsy." (PMID 26590798, 2015). "Therefore, LINC02242-hsa-let-7e-5p-KCNJ11 and LINC01963-hsa-miR-204-5p-KCNA1 might be involved in the regulation of epilepsy and brain injury." (PMID 37483435, 2023). "Common variants in KCNJ11 and BAD do not predict response to KDT for epilepsy." (PMID 26590798, 2015). "However, the involvement of KCNJ11 and KCNS1 in epilepsy has not been reported thus far, and it was first found that the mRNA and protein levels of these two genes were downregulated in TLE samples compared to normal controls, which remains to be confirmed by further studies." (PMID 37483435, 2023).
DEND syndrome (18 papers, 2013 to 2026). DEND syndrome is a very rare, generally severe form of neonatal diabetes mellitus (NDM) characterized by a triad of developmental delay, epilepsy, and neonatal diabetes. "In the present work, we reported a follow-up of a 24-year-old Brazilian male with DEND syndrome due to the KCNJ11 c.754G>A; p.(Val252Met) variant." (PMID 41169283, 2025). "There are currently no reported cases of this variant leading to DEND syndrome; however, for many KCNJ11 mutations, neurology appointments are highly recommended as approximately 25% of patients with KCNJ11 mutations develop DEND syndrome." (PMID 40309172, 2025). "The KCNJ11 mutation Q52R associates with DEND syndrome, although clinical phenotype and therapeutic options vary between patients." (PMID 35095528, 2021). "Neurological symptoms in Case 3 suggested DEND syndrome and a previously reported heterozygous KCNJ11 missense mutation, p.C166Y, was identified." (PMID 28943513, 2018). "Numerous gain-of-function mutations have been identified in the genes encoding Kir6.2 (KCNJ11) or the associated regulatory SUR1 subunit (ABCC8) of patients affected by DEND syndrome." (PMID 24062639, 2013). "Both the TNDM and PNDM, or DEND syndrome can result from mutations in KCNJ11 and ABCC8 genes." (PMID 34584998, 2021). "DEND syndrome is caused by R201C mutations in the KCNJ11 gene in one-fifth of the children." (PMID 34584998, 2021). "Gain of function mutations in the KCNJ11 gene, encoding the KIR6.2 subunit of the IKATP potassium channel, stand at the basis of most forms of DEND syndrome." (PMID 35095528, 2021).
developmental delay (17 papers, 2013 to 2026). "It is theorized that due to the presence of KATP channels in the brain, patients with KCNJ11 mutations exhibit an increased frequency of attention deficit disorder, sleep disruptions, developmental delays, and seizures." (PMID 40309172, 2025). "Of the patients carrying KCNJ11 and ABCC8 mutations, there was developmental delay in one patient diagnosed as iDEND, including one with congenital cataract." (PMID 26839896, 2016).
congenital hyperinsulinism (14 papers, 2013 to 2026). "While gain-of-function mutations in ABCC8 and KCNJ11 cause neonatal diabetes, loss-of-function (LoF) mutations typically cause congenital hyperinsulinism." (PMID 41614934, 2026). "Genetic screening identified an inactivating KCNJ11 mutation, which is believed to cause congenital hyperinsulinism (CHI)." (PMID 38152125, 2023). "Inactivating mutations in KCNJ11 or ABCC8 result in congenital hyperinsulinism (CHI) by enhancing ATP binding to the channel, leading to KATP channel closure, membrane depolarization, and insulin overproduction in the β-cell." (PMID 36361703, 2022). "The autosomal recessive form of persistent hyperinsulinemic hypoglycemia of infancy (PHHI) is associated with mutations in either ABCC8 or KCNJ11 genes." (PMID 25871929, 2015). "Mutations in ABCC8 (SUR1) or KCNJ11 (Kir6.2) can result in gain or loss of channel activity and cause neonatal diabetes (ND) or congenital hyperinsulinism (CHI), respectively." (PMID 25926814, 2015). "Individuals with LoF mutations in KCNJ11 (Kir6.2) suffer from congenital hyperinsulinism (CHI)." (PMID 37154692, 2023). "Mutations in ABCC8 and KCNJ11 are the most common cause of congenital hyperinsulinism (CHI)." (PMID 25584046, 2014).
Insulin resistance (13 papers, 2010 to 2024). Increased resistance towards insulin, that is, diminished effectiveness of insulin in reducing blood glucose levels. "Among numerous genetic loci, TCF7L2 (rs7903146), KCNQ1 (rs2237892), and KCNJ11 (rs5219) are associated with β-cell function, insulin resistance, and insulin action in GDM." (PMID 37107681, 2023). "Future longitudinal study will be required to establish the effect of E23K polymorphism in the KCNJ11 gene on changes of body build, insulin resistance, and β-cell dysfunction during disease progression." (PMID 25309595, 2014). "Mutations in the KCNJ11 gene may cause changes in the structure of the Kir6.2 protein and impair the functioning of the channel, which increases its activity and contributes to the development of insulin resistance." (PMID 34289004, 2021).
hyperinsulinemic hypoglycemia (10 papers, 2010 to 2023). An inherited autosomal recessive syndrome characterized by the disorganized formation of new islets in the pancreas and congenital hyperinsulinism. "Besides, several mutations on KCNJ11 gene have been reported to cause permanent hyperinsulinemic hypoglycemia of infancy." (PMID 25309595, 2014). "In animal models, Kir6.2-deficient mice show impaired glucose- and tolbutamide-induced insulin secretion, while in humans, KCNJ11 mutations underlie familial persistent hyperinsulinemic hypoglycemia of infancy and permanent neonatal diabetes, and are associated with common forms of T2D." (PMID 20936101, 2010).
heart failure (8 papers, 2015 to 2025). Inability of the heart to pump blood at an adequate rate to meet tissue metabolic requirements. "Genetic defects in the KCNJ11 gene have been previously associated with an increased risk of diabetic disorders and heart failure, by inducing changes in the heart's response to stress." (PMID 28727822, 2017). "SHapley Additive exPlanations analysis identified four key predictors: multivessel CABG (CABGVx ≥ 3), history of heart failure (HFHx), rs5219 (KCNJ11), and prolonged bypass duration (CABGTime)." (PMID 41020232, 2025). "Knockout of the KCNJ11 may lead to maladaptive remodeling and heart failure in hypertensive patients." (PMID 39854379, 2025).
Glucose intolerance (7 papers, 2008 to 2025). Glucose intolerance (GI) can be defined as dysglycemia that comprises both prediabetes and diabetes. "Furthermore, the KCNJ11 E23K variant was found to be associated with glucose intolerance and conversion from impaired glucose tolerance to T2D among Caucasians." (PMID 24710510, 2014). "Furthermore, the codon 23 KCNJ11 polymorphism is shown to be related to glucose intolerance in Caucasians and progression from glucose intolerance to T2D." (PMID 25309595, 2014). "Therefore, calcium ions are not able to influx from the extracellular space and there will be impaired secretion of insulin resulting in the defective metabolism of glucose and, for example, NDM-impaired fasting sugar, glucose intolerance, and KCNJ11-MODY." (PMID 38675722, 2024).
Impaired glucose tolerance (7 papers, 2014 to 2024). An abnormal resistance to glucose, i.e., a reduction in the ability to maintain glucose levels in the blood stream within normal limits following oral or intravenous administration of glucose. "One of those studies also observed impaired glucose tolerance and 60% reduced expression of KCNJ11 which encodes the Kir6.2 subunit of the potassium channel on the GLUT2 transporter, although this was not replicated in another study where expression of Kir6.2 was normal." (PMID 38933924, 2024). "In presence of family history of HY and/or Impaired Glucose Tolerance, Impaired Fasting Glucose or GDM, the hypothesis of ABCC8/KCNJ11, HNF1A or HNF4A gene mutations can be formulated." (PMID 32928245, 2020).
Arrhythmia (6 papers, 2008 to 2025). Any cardiac rhythm other than the normal sinus rhythm. "KATP is implicated in arrhythmia genesis, and mutations in genes coding for Kir6.2 (KCNJ11) and SUR2 (ABCC9) are linked to left ventricular hypertrophy and dilated cardiomyopathy in humans." (PMID 24477916, 2014). "Moreover, the KCNJ11 E23K variant has been associated with T2DM due to its impact on beta cell function and insulin release, and it has also been linked to cardiac arrhythmias in diabetic patients." (PMID 40303486, 2025).
Beckwith-Wiedemann syndrome (6 papers, 2022 to 2025). Beckwith-Wiedemann syndrome (BWS) is a genetic disorder characterized by overgrowth, tumor predisposition and congenital malformations. "ABCC8 and KCNJ11 are neighboring genes and they are located on the short arm of chromosome 11 in region 11p15 proximal to the imprinting region that when disrupted causes imprinting disorders Beckwith-Wiedemann syndrome (BWS) and Russell-Silver syndrome (RSS)." (PMID 36339418, 2022). "The chromosomal region 11p15, which harbors the ABCC8 and KCNJ11 genes, is also involved in several rare genetic syndromes associated with CHI, most notably Beckwith-Wiedemann syndrome (BWS)." (PMID 40904956, 2025). "In some cases, paternal isodisomy of chromosome 11p15 occurs in multiple tissues, causing Beckwith-Wiedemann Syndrome spectrum (BWSp); severe diazoxide-unresponsive HI can occur in BWSp due to 11pUPD when there is a concurrent paternally inherited ABCC8 or KCNJ11 disease-causing variant." (PMID 37454648, 2024). "Genetic studies were negative for mutations in ABCC8, KCNJ11, GCK, or GLUD1 genes, multiple endocrine neoplasia (MEN) type 1, and Beckwith-Wiedemann syndrome." (PMID 39170749, 2024).
breast carcinoma (6 papers, 2013 to 2025). "Here, we knock-downed of PSME2 and KCNJ11 in two breast cancer cell lines, MDA-MB-231 and MCF-7 cells." (PMID 38561760, 2024). "The KCNJ11 gene was markedly upregulated in kidney chromophobe and prostate adenocarcinoma, kidney renal papillary cell carcinoma, breast cancer, uterine carcinosarcoma, and uterine corpus endometrial carcinoma." (PMID 37180726, 2023). "This SNP is also highly significantly associated with expression of NCR3LG1, KCNJ11, and SNORD14 genes with fragmentary and elusive data on association with breast cancer." (PMID 33334016, 2020). "However, in the TNBC subtype, we observed an opposite expression pattern: CACNA1H and KCNJ11 were significantly downregulated compared to other breast cancer subtypes, whereas S100B showed markedly elevated expression." (PMID 40606662, 2025). "Next, to investigate whether KCNJ11 influenced the cell viability, clone formation, or migration of breast cancer cells, KCNJ11 was knockdown in MCF-7." (PMID 38561760, 2024). "When searching in Pubmed, the research about KCNJ11 and breast cancer was rare." (PMID 38561760, 2024). "Among these nine screened genes, most of them were well-studied in breast cancer, except PSME2 and KCNJ11." (PMID 38561760, 2024). "In accordance with the gene expression levels, the protein levels of ZDHHC9, PCMT1, TMEM70 were significantly higher in breast cancer, and the protein levels of IRF2, KCNJ11 were higher in normal tissues." (PMID 34956313, 2021). "In the experiment part, the down-regulation of PSME2 inhibited cell growth ability and clone formation capability of breast cancer cells, while the down-regulation of KCNJ11 did not have any functions." (PMID 38561760, 2024). "The data presented here indicated that KCNJ11 played no role in the breast cancer cell’s growth and migrate." (PMID 38561760, 2024). "We tested the role of the ABCC8/Sur1, ABCC9/Sur2A/B, KCNJ11/Kir6.2, and KCNJ8/Kir6.1 genes experimentally in a minoxidil-induced renal tumor in male rats and in the female canine breast cancer, a spontaneous animal model of disease, and in the pharmacovigilance and omics databases." (PMID 37180726, 2023). "Yet, the relationship between KCNJ11 and breast cancer has not been systematically reported." (PMID 34956313, 2021).